APC (APC regulator of Wnt signaling pathway)
Diseases named in the same sentence as APC in open-access papers (continued):
Sharing a sentence is not in itself a finding about the gene and the disease.
colon carcinoma (continued). "Next, we examined whether SMA could exert anti-proliferative activity in A549 human non-small cell lung cancer cells (NSCLC), which possess mutant APC and wild type β-catenin similar to HT29 colon cancer cells." (PMID 26544726, 2015). "Studies were performed to determine if E7449-mediated tankyrase inhibition could affect Wnt signaling in human colon cancer SW480 (Wnt active, APC mutant) cells in vitro." (PMID 26513298, 2015). "APC/b-catenin pathway dysregulation, which is also commonly observed in desmoid tumors, may directly regulate COX-2 expression in colon cancer." (PMID 24213228, 2012). "APC and CMTM3, EXO1 and HLTF are reported to be hyper-methylated in selected colon cancer samples." (PMID 22051105, 2011). "In the presence of Wnt, or the absence of APC (as occurs in many colon cancers), β-catenin target genes including c-myc are expressed." (PMID 19822006, 2009). "The synchronous colon cancers did not lead to clinical suspicion of FAP, but the development of extracolonic features linked to FAP prompted APC mutation analysis, which identified an insertion (c.5030_5031insAA) in the 3'end of the gene." (PMID 19036155, 2008). "However, the majority of colon cancers are MSS, which are driven by APC inactivation." (PMID 40385346, 2025). "In addition, eight proteins were significantly correlated with the OS of APC-MUT colon cancer patients (Cox proportional hazards regression analysis, p < 0.05) but were not correlated with that of APC-WT colon cancer patients." (PMID 36934880, 2023). "In addition, five phosphosites were significantly correlated with the OS of APC-MUT colon cancer patients (Cox proportional hazards regression analysis, p < 0.05) but were not correlated with that of APC-WT colon cancer patients." (PMID 36934880, 2023). "GO enrichment analysis showed that specific proteins, including TGFβ1, adenomatous polyposis coli (APC), CTNB1, low-density lipoprotein receptor-related protein (LRP) 5 (LRP5), LRP6, JAK1, ST14, and TP53BP1, were hypothetical CD151-interacting proteins in colon cancer." (PMID 33767593, 2021). "However, no mutations were detected in either APC or KRAS, suggesting that mutated CTNNB1 is the driver in colon cancer development induced by PhIP/DSS." (PMID 34488905, 2021). "Likewise, bazedoxifene treatment of human colon cancer cells harboring mutant APC did not reduce aberrant canonical WNT signaling, but suppressed IL11‐dependent STAT3 signaling." (PMID 30885958, 2019). "In the APC gene knockout animal model, which develops multiple intestinal adenomas, acarbose had a regressive effect on the size of gastrointestinal adenomas but did not significantly decrease the number of colonic neoplasms." (PMID 29113364, 2017). "To test this hypothesis, we used human colon cancer cells RKO, which in contrast to CACO-2 and HCT-116, do not contain mutations in β-catenin or APC." (PMID 25929479, 2015). "We investigated whether SMA suppresses colon cancer proliferation by using a colony formation assay in HT29 cells, which possess an APC mutation, and CT26 cells, which do not." (PMID 26544726, 2015). "Indeed, whereas both the KD of SOX12 and TMED3 are effective in CC14 (with undetermined APC status in this non-clonal primary colon cancer cell population), TMED3 KD has diminished potency in comparison with KD of SOX12 in HT29." (PMID 24920608, 2014).
colon carcinoma (continued). "Similarly to APC mutant colon tumours, we do not observe nuclear β-catenin throughout the CU-PC01 tumours, indicating that the additional deregulation of the Wnt pathway from the tumour microenvironment is also involved in activating the pathway even in CTNNB1 mutant cells." (PMID 38667288, 2024). "We confirmed that Lrp6 endocytosis was observed in SW480, a colon cancer cell line in which the absence of APC triggered, and APC reconstitution inhibited, Wnt signaling and Lrp6 endocytosis; this is in agreement with recent results showing that APC is a major regulator of endocytosis." (PMID 33299006, 2020). "Thus, the original hypothesis that expression of PPARβ/δ is increased by APC/β-CATENIN/TCF4 signaling in colon cancer is not supported by many subsequent studies." (PMID 31602402, 2019). "Since N-terminally truncated fragments of human APC can rescue ßcat degradation in human colon cancer cells, it is not inconceivable that APC233 or even APC219–33 might encode very low levels of an N-terminally truncated APC2 protein that nonetheless retained some function in Wnt regulation." (PMID 22359584, 2012). "Tumors were absent in APC and KRAS mut mice not treated with DSS, while APC; KRAS mut mice developed small proximal colon tumors." (PMID 41285904, 2025). "For example, it has been shown that APC down-regulation in CBS and Moser colon cancer cells converts the negative effect of TGFβ on wnt signalling into a positive one, without altering the amount of nuclear β-catenin." (PMID 22509309, 2012).
adenoma (503 papers, 1989 to 2026). A neoplasm arising from the epithelium. "Development of adenoma is triggered by acquisition of additional loss-of-function variants or deletions in the opposing APC allele, leading to the formation of numerous adenomas." (PMID 41214301, 2026). "Adenoma density is associated with the location of the germline variant in the APC gene and with the risk of development of CRC." (PMID 41214301, 2026). "Yet, in adenoma cells with mutated APC, CtBP can bind to truncated APC’s C-terminal and act as an oncogene, as we observed in this study, via reported oncogenic mechanisms." (PMID 39977302, 2025). "In the colon epithelium, it causes the progression of adenomas that are triggered by the loss of tumor suppressor adenomatous polyposis coli (APC)." (PMID 39786607, 2025). "In contrast, conventional tubulovillous adenomas arise through constitutive epithelial wnt activation as a consequence of initiating APC mutation in crypt base columnar cells, and have only stromal expression of Grem1." (PMID 40467544, 2025). "The initial oncogenic event in CRC is defined by a mutation targeting the adenomatous polyposis coli (APC) gene, a well‐known tumor‐suppressor gene that provokes the development of benign adenomas or colorectal polyps." (PMID 40468102, 2025). "For instance, monoclonal lesions rarely exhibit more than two APC mutations, in contrast to polyclonal adenomas that are more genetically diverse." (PMID 40451939, 2025). "APC mutations were observed in 75% of the colorectal adenomas, and the frequency of the mutation was sustained through the adenoma-carcinoma sequences." (PMID 41488735, 2025). "The colibactin-associated APC mutations have been identified in a relevant number of adenomas and tumours from patients with unexplained adenomatous polyposis, demonstrating a bacterial aetiology." (PMID 40237887, 2025). "In contrast, APC mutations in sporadic adenomas were more widely distributed in the 5′- half of the gene." (PMID 41488735, 2025). "Studies of adenomas from patients with attenuated FAP have further revealed third hits in APC targeting the germline mutant allele to achieve an optimal genotype." (PMID 41488735, 2025). "Patients with FAP have an autosomal dominant mutation in the adenomatous polyposis coli (APC) gene that predisposes them to developing numerous adenomas." (PMID 40429526, 2025). "A recurrent pathogenic APC variant (NM_00038.5:c.2803_2804insC) was detected in all adenomas tested." (PMID 40956995, 2025). "Loss of APC function due to germline mutations is an early and critical event in the adenoma-carcinoma sequence." (PMID 40702333, 2025). "Among these, APC mutation is considered the gate keeper event in early adenoma formation, leading to aberrant activation of the WNT/β-catenin pathway." (PMID 40919165, 2025). "Recent studies have demonstrated that APC mutations are less common in duodenal carcinomas, suggesting that the adenoma–carcinoma sequence is limited to intestinal-type duodenal carcinomas." (PMID 40463821, 2025). "If the only available non-haematopoietic tissue source consists of gastrointestinal neoplasms (adenomas or cancer), at least two independent lesions should be analysed to confirm the presence of a common APC variant in all of them." (PMID 40237887, 2025).
adenoma (continued). "Our in vitro findings using human colon-derived cells provide a strong preclinical foundation for the establishment of clinical trials aimed at delaying or preventing the adenoma-carcinoma transition in FAP1 patients carrying similar APC mutations." (PMID 40702333, 2025). "The adenoma-carcinoma pathway involves early mutations in the tumor suppressor gene adenomatous polyposis coli (APC) and subsequent chromosomal instability (CIN)." (PMID 41150213, 2025). "YAP activation in human colorectal adenoma was significantly correlated with APC mutations, Wnt activation, and advanced adenoma odds." (PMID 39977302, 2025). "FBXW7 loss promotes intestinal tumorigenesis by enhancing proliferation, disrupting differentiation, causing DEK accumulation, altering TPM splicing, and accelerating adenomas with APC deficiency." (PMID 41373479, 2025). "The Apcmin/+ model drives adenoma‐carcinogenesis through APC gene mutation‐induced hyperactivation of the Wnt/β‐catenin signaling pathway." (PMID 40859429, 2025). "Inactivation of APC is the initiating mutation in approximately 80–85% of sporadic CRCs, marking the onset of the adenoma–carcinoma sequence." (PMID 41228231, 2025). "CRC and adenoma patients were comparable in terms of age, sex, BMI, smoking status, APC and KRAS mutational status." (PMID 39980011, 2025). "Our genetic analysis indicated a high frequency of APC somatic mutations in adenomas of both FAP patients and sporadic cases." (PMID 41488735, 2025). "Although the PIGA mutant allele frequency varied considerably between adenomas, it was above the median mutant allele frequency for the corresponding adenoma in most cases, a pattern similar to APC, and consistent with occurrence early in tumorigenesis." (PMID 38546397, 2024). "The key pathway recognized in the alteration of the normal epithelium to adenoma is mutation or epigenetic changes in the APC/Wnt/β-catenin pathway." (PMID 39456841, 2024). "Specifically, APC mutations correlated with the formation of polyps, which can progress to adenomas and eventually carcinoma." (PMID 39273409, 2024). "The observation that the KRAS mutation was absent in the normal mucosa was not controversial and supports current belief that KRAS-activating mutations occur later in the adenoma-carcinoma progression model, after APC driver mutations." (PMID 39507544, 2024). "Since a large proportion of our unexplained polyposis patient cohort showed a colibactin-associated APC variant in multiple adenomas, further research into the presence and impact of colibactin and its mutational signature was warranted." (PMID 38238650, 2024). "Although control LS adenomas acquired variants in APC at a higher rate than the tumors of LS-298 (48% (12/25) versus 26.67% (4/15), respectively), the difference was not statistically significant." (PMID 38725616, 2024). "More than 80% of adenomas exhibit APC mutations, and an additional 5–10% have mutations or epigenetic changes in other parts of the WNT signaling pathway, such as β-catenin." (PMID 38674816, 2024). "Carriers of COX-2 A-1195G AG increase adenomas and CRCs risk, and mutation in the APC gene has been shown to correlate with COX-2 expression in both adenomas and CRCs." (PMID 40171463, 2024). "Similar results were observed in APCMin/+ mice with induced adenoma carrying a loss-of-function germinal mutation in the APC gene." (PMID 38279052, 2024).
adenoma (continued). "Low-frequency APC mutations in SSLs/SSLDs are in contrast to conventional adenomas, which show APC mutations in more than 90% of cases as an initial event in the adenoma–carcinoma sequence." (PMID 37219625, 2023). "For most adenomas and carcinomas in the colon and rectum and some in the stomach, inactivating both alleles of the APC gene is necessary as an early event." (PMID 37577746, 2023). "The most common initiating mutations of the adenoma to carcinoma sequence, APC and KRAS, increase proliferation, protein translation, and stemness." (PMID 37643866, 2023). "In the group of genes (1069) found to be mutated both in adenoma and carcinoma samples, the most frequently mutated genes were APC (AD: 17/27, CRC: 33/51 (0.647)) and KRAS (AD: 8/27, CRC: 21/51 (0.412))." (PMID 36765865, 2023). "Although CRC develops predominantly from the adenoma–adenocarcinoma sequence through APC gene mutations, in recent years, studies have demonstrated the role of chronic inflammation in this neoplasia pathogenesis." (PMID 38137862, 2023). "Among the key driver genes that play role in carcinogenesis, the adenomatous polyposis coli (APC), accompanied by its mutations, regulates growth advantages in epithelial cells and results in the formation of a small adenoma." (PMID 37345083, 2023). "APC is the most frequently mutated gene in this type of cancer and APC mutant cells need to outcompete wild-type intestinal stem cells within the colon crypts, resulting in the homing of the mutant cells, which drives adenoma formation." (PMID 37143081, 2023). "CRC progress in a multistep pattern from early adenoma to late-stage adenocarcinoma through the accumulation of many genetic and epigenetic events initiated by APC mutation and chronic inflammation." (PMID 37648713, 2023). "In CRC, the first mutations usually concern the APC gene resulting in a proliferative advantage of epithelial cells promoting benign lesions (small adenomas)." (PMID 37538108, 2023). "It has been found that APC deletion/loss of function leads to CRC development, while restoring APC function can regress adenomas by reducing Wnt activity." (PMID 36765950, 2023). "APC mutated small adenomas have a slow growth rate, but further mutations of the KRAS gene can increase their proliferation." (PMID 37538108, 2023). "Carriers of the APC mutation typically develop classic colonic polyposis with 100 to 1000 adenomas and show close to a 100% lifetime risk for CRC." (PMID 37444619, 2023). "As major conclusions, this study for the first time directly demonstrates that an intact Pkd1 gene supports early stages of CRC formation, and that loss of PKD1 is tumor suppressive in adenoma formation mediated by loss of APC in a mouse model." (PMID 37542051, 2023). "FAP-associated adenomas arise from APC germline mutation that can switch on WNT/beta-catenin mediated transcription, stimulating the transition of intestinal crypts to precursor lesions, such as tubular or villous adenomas." (PMID 37345083, 2023).